VIM (vimentin)
Diseases named in the same sentence as VIM in open-access papers (continued):
Sharing a sentence is not in itself a finding about the gene and the disease.
lung adenocarcinoma (continued). "For example, doxorubicin‐induced senescence in A549 lung adenocarcinoma cells also led to changes in vimentin filament organization." (PMID 35122388, 2022). "Recent studies by our research group have revealed that the overexpression of RUNX2 in lung adenocarcinoma is involved in epithelial-mesenchymal transition through transcriptional regulation of the VIMENTIN, TWIST1, and SNAIL1 genes." (PMID 36510562, 2022). "In our laboratory, RUNX2 has been related to the positive regulation of gene expression associated with EMT, such as vimentin and SNAIL1, thereby increasing the migratory capacity of lung adenocarcinoma cells." (PMID 36551878, 2022). "In this case, the immunohistochemical results of CK7, Napsin A and TTF-1 supporting the diagnosis of lung adenocarcinoma were all positive, and the immunohistochemical results of Vimentin, CD10 and PAX-8 supporting the diagnosis of RCCC were all positive." (PMID 35979370, 2022). "Silibinin regulated β-catenin, E-cadherin, N-cadherin, and vimentin proteins in lung adenocarcinoma cells inhibited cancer cell invasion." (PMID 33935737, 2021). "Through RNA interference experiments in three lung adenocarcinoma cells, we found that the knockdown of TdIF1 upregulates the expression level of E-cadherin while downregulating the expression of N-cadherin and vimentin." (PMID 35008676, 2021). "The phosphorylation of vimentin was accompanied by the activation of PLK1 during TGF-β-induced EMT in lung adenocarcinoma." (PMID 33963314, 2021). "Amplified expression of miR‐144 leads to decreased Vimentin and elevated E‐cadherin in lung adenocarcinoma cells." (PMID 33417281, 2021). "Here, the authors identify VAL (Vimentin associated lncRNA) to be directly induced by AKT/STAT3 signaling and report a lncRNA-mediated mechanism for active AKT-driven EMT-independent lung adenocarcinoma metastasis." (PMID 33046716, 2020). "EZH2 and the EMT markers E-cadherin and Vimentin were examined by IHC in lung adenocarcinoma specimens that were resected from 2003–2012." (PMID 31042721, 2019). "In support of this, in lung adenocarcinomas, glycosylated vimentin was shown to be frequently downregulated, defining its potential as a biomarker both for treatment and diagnosis." (PMID 30248895, 2018). "Further study with sorted cells as keratin/vimentin expression ratios is needed for assessing EMT characteristics in lung adenocarcinoma." (PMID 29525983, 2018). "Meanwhile, GGPPS inhibition significantly increased the expression of E‐cadherin and reduced the expression of N‐cadherin and vimentin in lung adenocarcinoma cells." (PMID 29377583, 2018). "AFG1-induced lung adenocarcinoma expressed high levels of vimentin, α-SMA, and Twist1 in cancer cells." (PMID 28801561, 2017). "ACTA2 silencing significantly increases E-cadherin expression but decreases vimentin expression in lung adenocarcinoma cells." (PMID 28881584, 2017). "Here, we found increased SOD-2 expression associated with vimentin, α-SMA, Twist1, and MMP upregulation in AFG1-induced lung adenocarcinoma." (PMID 28801561, 2017). "Vimentin has been regarded as a novel marker, with preferentially expressed in moderately and well-differentiated lung adenocarcinomas." (PMID 28039472, 2017). "As expected, we observed increased expression of mesenchymal markers Vimentin, Snail and Zeb1 and decreased expression of epithelial markers including E-cadherin and Claudin1 following treatment of lung adenocarcinoma cell lines with drugs." (PMID 28186986, 2017). "To validate these observations, we quantified the expression of ZEB1, CDH1 and VIM for 41 paired samples of lung adenocarcinoma and adjacent normal lung tissues." (PMID 27456471, 2016). "A progressive increase in the levels of alpha-SMA, vimentin and CK-19 was observed in correlation to the degree of malignancy from normal lung tissue to lung adenocarcinoma with lymphatic metastasis, whereas E-cadherin expression showed the opposite trend." (PMID 25189096, 2014).
lung adenocarcinoma (continued). "We also used immunofluorescence assays to determine the protein levels of E-cadherin and vimentin in lung adenocarcinoma tissue samples with low IL-6 or high IL-6 expression." (PMID 24789104, 2014). "In HBE, a lung normal bronchial epithelial cell line, and A549, a lung adenocarcinoma cell line, GnT-V protein levels were relatively high, which were correlated with E-cadherin expression positively and N-cadherin/Vimentin expression negatively." (PMID 24913443, 2014). "Vimentin overexpression has been detected in several types of tumors, including lung adenocarcinoma, and its expression is correlated with tumorigenesis, invasion, and metastasis." (PMID 25189096, 2014). "Decreased E-cadherin expression or gain of vimentin expression is closely correlated with various indices of lung adenocarcinoma progression, including the grade, local invasiveness, dissemination into blood, and tumor relapse after radiotherapy." (PMID 23049725, 2012). "We have shown that loss of SARI expression initiates epithelial-mesenchymal transition (EMT), which is visualized by repression of E-cadherin and up-regulation of vimentin in lung adenocarcinoma cell lines and in clinical lung adenocarcinoma specimens." (PMID 23049725, 2012). "Loss of SARI and E-cadherin and increased vimentin, p-GSK-3β, and β-catenin levels were clearly detected in tissues from lung adenocarcinoma patients with lymph node metastasis." (PMID 23049725, 2012). "Loss of SARI and E-cadherin and increased vimentin and p-GSK-3β were clearly detected in tissues from lung adenocarcinoma patients who had lymph node metastasis." (PMID 23049725, 2012). "Also, we demonstrated that vimentin shows EMT-related morphology under hypoxic conditions in lung adenocarcinoma cells." (PMID 39227650, 2024). "Importantly, keratin 16 overexpression promotes lung adenocarcinoma metastasis by stabilizing the structural protein vimentin, which is essential for metastasis driven by keratin 1644." (PMID 39739089, 2024). "Moreover, Trim16-dependent vimentin polyubiquitination and degradation was reported in lung adenocarcinoma that was diminished by AKT-induced lncRNA VAL." (PMID 36631457, 2023). "Studies have found that vimentin is essential for the early metastasis of lung adenocarcinoma." (PMID 36412203, 2023). "Therefore, we measured EMT-related factors, E-cadherin, N-cadherin, and vimentin, in vitro after the knockdown of TdIF1 in three lung adenocarcinoma cell lines." (PMID 35008676, 2021). "Similar findings were generated by immunohistochemistry on metastatic and nonmetastatic lung adenocarcinomas, suggesting that TF/vimentin association is an early cancer marker." (PMID 32152404, 2020). "Moreover, silencing of PODXL level in human lung adenocarcinoma cells decreased the spreading and migration abilities and resulted in the phenotype changes of cells by affecting EMT-associated protein, such as vimentin and E-cadherin." (PMID 29748877, 2019). "In work carried out on a panel of lung adenocarcinoma cell lines we found that ectopic RAC1B expression was associated with increased E-cadherin and decreased Vimentin expression and in contrast to RAC1 was unable to induce EMT and invasive activity in an in vivo chorioallantoic invasion model." (PMID 31817229, 2019). "Furthermore, we analyzed the expression of RUFY3 and EMT markers (E-cadherin, N-cadherin, Vimentin and Slug) in 2 lung adenocarcinoma cell lines after RUFY3 silencing by Western blot." (PMID 31772661, 2019). "Similarly, we confirmed that, in lung adenocarcinoma, miR-24-3p suppressed the expression of FGFR3 as well as some EMT-associated factors, including Snail, E-cadherin, and Vimentin." (PMID 29850625, 2018). "Accordingly, we examined the expression of IL-6, E-cadherin and vimentin mRNA in tissue samples from 18 cases of lung adenocarcinoma, and 6 corresponding paracancerous tissues, by quantitative PCR, and analyzed the correlation between IL-6 and E-cadherin or vimentin expression." (PMID 24789104, 2014).
lung adenocarcinoma (continued). "Furthermore, in vitro experiment using siRNA knocking down the COL5A1 expression of myofibroblasts and co-culturing with lung adenocarcinoma cells, the Vimentin expression was downregulated, as well as the migration and invasion ability of lung adenocarcinoma cells." (PMID 38987529, 2024). "Following phosphotyrosine 380 of caspase-8–mediated c-Src overactivation, we detected the downregulation of E-cadherin and upregulation of vimentin with morphological characteristics of spindle and dendritic shapes that could promote tumor metastasis in lung adenocarcinoma." (PMID 34367939, 2021). "Additionally, it was found that the altered expression of PODXL lead to the molecular changes (e.g., vimentin, E-cadherin, collagen I) associated with TGF-β induced EMT of human lung adenocarcinoma cells, demonstrating the significant role of PODXL in the EMT and metastasis of cancers." (PMID 29748877, 2019). "A more recent study showed that vimentin expression in cancer-associated fibroblasts is required for dissemination of early stage lung adenocarcinoma, which indicates that vimentin might have a key role in the cancer-promoting capacity of cancer-associated fibroblasts in the tumour microenvironment." (PMID 30248895, 2018). "Interestingly, the isoform of vimentin was only found in 4 of the cell lines analyzed (in the Panc-1 pancreatic, in the H23 and A549 lung adenocarcinoma, and in the Hs1 testes tumor cell lines), thus suggesting that expression of the antigenic isoform was cell line-specific." (PMID 18769604, 2006). "In HEK-293T cells, TGFB1 overexpression increased β-catenin and Snail expression, accompanied by a corresponding downregulation of E-cadherin and Vimentin, indicating that TGFB1 strongly promotes EMT in EGFR-mutant lung adenocarcinoma cells." (PMID 40234395, 2025). "PIK3C2B expression showed significant positive correlations with key EMT regulators: SNAI1 (r = 0.11, p = 0.00098), VIM (r = 0.21, p = 1e-10), ZEB1 (r = 0.37, p = 6.7e-33), and TWIST2 (r = 0.11, p = 0.00034) in TCGA lung adenocarcinoma samples." (PMID 41362647, 2025). "In lung adenocarcinoma cell lines (A549 and H1975), POSTN silencing upregulates the epithelial marker E-cadherin and downregulates the mesenchymal markers N-cadherin and Vimentin; conversely, POSTN overexpression exerts the opposite effect." (PMID 40991535, 2025). "Overexpression of TRIM21 reduced the promoting effect of ZSWIM1 on the proliferation, migration, and invasion of lung adenocarcinoma cells, and reversed the impact of ZSWIM1 on the expression of E-cadherin and Vimentin." (PMID 38880921, 2024). "Low FBXO11 expression in lung adenocarcinoma cells increases ZEB1 protein levels, decreases epithelial marker E-cadherin, and increases mesenchymal markers N-cadherin and vimentin, promoting EMT and enhancing cell migration and invasion." (PMID 39409891, 2024). "After detecting the expression of EMT and metalloproteinase-related genes in lung adenocarcinoma cells co-cultured with M2-like macrophages, we found that the expression of EMT-related genes (E-cadherin, N-cadherin, Snail, Vimentin) was highly variable." (PMID 38424624, 2024). "Previous studies by our research group showed that the silencing of RUNX2 in lung adenocarcinoma affected the transcriptional activation of the TWIST, SNAIL-1, and VIMENTIN genes, which also impacted the cell migration capacity." (PMID 37754231, 2023). "It is characterized by decreased E-cadherin expression and vimentin overexpression, and also participates in the mechanism of TKI resistance in EGFR-mutant lung adenocarcinoma." (PMID 37340370, 2023). "Phosphorylated vimentin activates TGF-β signaling, leading to metastasis and PDL1 expression for immune suppression in lung adenocarcinoma." (PMID 36717839, 2023). "In lung adenocarcinoma cells, AQP1 overexpression correlated with the downregulation of E-cadherin and the upregulation of vimentin." (PMID 35847914, 2022).
lung adenocarcinoma (continued). "Here, we show that vimentin phosphorylated by PLK1, triggers TGF-β-signaling, which consequently leads to metastasis and PD-L1 expression for immune suppression in lung adenocarcinoma." (PMID 33963314, 2021). "Right supraclavicular lymph node biopsy was performed, and pathological examination allowed diagnosis of lung adenocarcinoma T2N3M1a, and immunohistochemistry (IHC) revealed the tumor to be NapsinA+, TTF-1+, CK7+, CD10−, and vimentin+." (PMID 34745948, 2021). "Lung adenocarcinoma was positive for MCK and TTF-1, and MGs showed immunoreaction for Vimentin, Desmin and SMA; Ki67 expression of classical OPA was higher than atypical OPA and MGs." (PMID 32807166, 2020). "To further investigate the relation between SOD-2 overexpression and EMT, we examined the well-defined markers of EMT, including E-cadherin, vimentin, α-SMA, and Twist1 in AFG1-induced lung adenocarcinoma." (PMID 28801561, 2017). "The expression of TNF-α, IL-6, and macrophage marker CD68, as well as E-cadherin, vimentin, Twist, matrix metalloproteinase (MMP)-2, MMP-9, and SOD-2 were examined in AFG1-induced lung adenocarcinoma." (PMID 28801561, 2017). "In lung adenocarcinoma patients, EDIL3 expression was significantly correlated with low e-cadherin expression, high vimentin expression, and increased microvessel density (P < 0.001, P = 0.001, and P = 0.023, respectively)." (PMID 28819306, 2017). "Western blot results showed elevated expression of vimentin, α-SMA, and Twist1, while lower expression of E-cadherin, in the lung tissues of mice with AFG1-induced lung adenocarcinoma." (PMID 28801561, 2017). "We characterized three lung adenocarcinoma cell lines H1299, H2291, and H1975 for their EMT status by immunofluorescence (IF) staining with canonical EMT markers - CDH1 (E-cadherin) and VIM (Vimentin)." (PMID 27008704, 2016). "if both renal cell carcinoma and lung adenocarcinoma are in the differential diagnosis based on morphology and/or clinical history a broad IHC panel including TTF-1, PAX-8 and vimentin should be applied for a definitive diagnosis." (PMID 25889632, 2015). "Similarly, expression of mesenchymal markers including Vimentin and Zeb1 were significantly increased following EerI treatment and returned to basal level after PP2 treatment further providing evidence that PP2 blocks ER stress and its associated EMT in lung adenocarcinoma cells." (PMID 25970786, 2015). "In this study, using a tissue array method, we investigated the expression of known EMT-related proteins including cytokeratin, E-cadherin, TTF-1, β-catenin, vimentin, Snail, Twist, CD44 in lung adenocarcinoma patients’ samples." (PMID 23706092, 2013). "The expression of EMT-related proteins including cytokeratin, E-cadherin, TTF-1, β-catenin, vimentin, Snail, Twist, CD44 was evaluated by immunohistochemistry using a tissue array method in the lung adenocarcinoma tissues of 95 patients." (PMID 23706092, 2013). "Expression of TWIST1, mesenchymal (CDH2, VIM, SNAI1, ZEB1) and epithelial (CDH1, JUP) markers in lung adenocarcinoma cell lines." (PMID 22272264, 2012). "To test the hypothesis that WFA disrupts vimentin IFs and impairs migration and invasion in vitro, we treated KPV+/+ cells and human lung adenocarcinoma (A549) cells with WFA." (PMID 37161053, 2023). "Immunohistochemical characterization of six tumor regions was done for ALK and markers of lung adenocarcinoma (NKX2.1), epithelial (E‐cadherin, pan‐cytokeratin, and cytokeratin 18) and mesenchymal (vimentin) phenotypes, tumor vasculature (CD31), and basement membrane organization (collagen type IV)." (PMID 36423211, 2023). "After treatment with the PI3K inhibitor and EGF, the expression levels of E-cadherin and Vimentin recovered, indicating that LncRNA-AC009948.5 could promote EMT in lung adenocarcinoma cells through the PI3K/Akt/GSK3β signaling pathway." (PMID 36059662, 2022). "Vimentin is a key factor linking EMT and EZH2 in lung adenocarcinoma." (PMID 31042721, 2019).
lung adenocarcinoma (continued). "According to this data, LMN (lamin), VIM (vimentin), TUB (tubulin), and ACT (actin) detected with the help of aptamers LC-18, LC-17, and LC-24 are involved in cancer progression and could act as lung adenocarcinoma biomarkers." (PMID 29137182, 2017). "Western blot analysis revealed significantly decreased expression of the epithelial marker E-cadherin and increased expression of the mesenchymal marker Vimentin following treatment with thapsigargin, indicating ER stress induced EMT in lung adenocarcinoma cell lines." (PMID 28186986, 2017). "Our in vivo experiments confirmed that M2 macrophages could significantly up-regulate the expression of Vimentin, LeY and p-Ezrin and down-regulate the expression of E-cadherin, thus promote the growth and EMT of lung adenocarcinoma xenograft." (PMID 28423676, 2017). "Consistently, immunohistochemical staining results showed that lung adenocarcinoma cells expressed high levels of E-cadherin but low to non-detectable levels of Vimentin and ZEB1." (PMID 27456471, 2016). "In the present study, the cancer cells of lung adenocarcinomas containing an MPP were found to express vimentin more extensively than those in lung adenocarcinoma without an MPP." (PMID 25120667, 2014). "As expected, we found reduced E-cadherin expression and enhanced vimentin expression in HCC827-pSB388 tumors compared with HCC827 tumors, further supporting the in vitro findings that IL-6 could induce EMT of lung adenocarcinoma cells." (PMID 24789104, 2014). "We conclude that negative expression of both myosin IIA and vimentin is an indicator of good prognosis for stage I lung adenocarcinoma without the need for PAC." (PMID 18212748, 2008). ", These experimental results suggest a close correlation between changes in LINC01117 expression and the expression levels of EMT-related markers such as E-cadherin, N-cadherin and Vimentin, strongly suggesting that LINC01117 may regulate lung adenocarcinoma progression by affecting EMT process." (PMID 37384755, 2023). "Interestingly, among the other defective pathways in the MPM group, one (R-HSA-8941326) affects RUNX2, the master gene in osteogenesis, which has been shown to increase expression of EMT genes (included in R-HSA-8941326) vimentin, TWIST1 and SNAIL1 in lung adenocarcinoma cells." (PMID 36362413, 2022). "Moreover, in lung adenocarcinoma cells, AQP1 overexpression showed certain cellular characteristics of EMT, including decreased expression of E-cadherin and increased expression of known EMT regulated proteins, such as vimentin and N-cadherin." (PMID 35847914, 2022). "To further address the clinical relevance of this hypothesis, we first utilized our proteomic and transcriptomic data from a prospectively collected lung adenocarcinoma cohort of Taiwan Cancer Moonshot to examine the correlation between MTAP/vimentin and PRMT5/vimentin." (PMID 35766227, 2022). "Thus, PLK1-mediated phosphorylation of vimentin activates TGF-β signaling pathway, leading to the metastasis and immune escape through the expression of PD-L1, functioning as a shuttling protein in lung adenocarcinoma." (PMID 33963314, 2021). "In addition, miRNA-214 up-regulated vimentin expression and promoted the EMT, which resulted in the metastasis of lung adenocarcinoma via suppressor-of-fused protein, and the decreased expression of miRNA-30c may induce the EMT and result in the invasion of NSCLC." (PMID 27657690, 2016). "Consistency of these findings with the clinic is shown by the fact that in samples of 10 lung adenocarcinoma specimens derived from the tumor center, however, all invasive tumor cells strongly expressed PCK but not vimentin." (PMID 35565305, 2022). "The clinical correlation between expression of both vimentin and PLK1, and overall survival rates of patients was significant in lung adenocarcinoma but not in squamous cell carcinoma." (PMID 33963314, 2021).